IDH2 (isocitrate dehydrogenase (NADP(+)) 2)
Diseases named in the same sentence as IDH2 in open-access papers (continued):
Sharing a sentence is not in itself a finding about the gene and the disease.
acute myeloid leukemia (continued). "Mutations of IDH2 at R140 and R172 residues are observed in 20% of acute myeloid leukemias (AML), and the availability of the IDH2 inhibitor Enasidenib made IDH2 mutational screening a clinical need." (PMID 32629801, 2020). "Mutations in IDH1 and IDH2 (Isocitrate dehydrogenase) genes are found in different cancers, including glioblastoma and acute myeloid leukemia (AML)." (PMID 32397535, 2020). "Driver mutations in IDH1 and IDH2 have been likewise identified in acute myeloid leukemia (AML), chondrosarcoma, myelodysplastic syndromes, and cholangiocarcinoma." (PMID 31165048, 2019). "However, IDH1 and IDH2 mutations are also found in acute myeloid leukaemia (AML)." (PMID 23894344, 2013). "This study reveals causality‐enriched epigenetic clocks offer additional insight into acute myeloid leukemia (AML) specific DNA methylation remodeling, particularly when integrated with genetic stratification, like DNMT3A or IDH2 mutations." (PMID 41556261, 2026). "Insights from acute myeloid leukemia suggest that receptor tyrosine kinase mutations, secondary IDH mutations, and isoform switching (e.g., IDH1 to IDH2) can mediate resistance." (PMID 41008893, 2025). "Mutations in isocitrate dehydrogenase (IDH), particularly in IDH1 and IDH2, have emerged as critical molecular events in various cancers, most notably gliomas, acute myeloid leukemia (AML), and chondrosarcomas." (PMID 40724998, 2025). "Mutant IDH1 and IDH2 generate 2-hydroxyglutarate, disrupt TET2 function, enforce DNA hypermethylation, and impair differentiation in acute myeloid leukemia, showing that metabolic alterations can be causal rather than merely correlative." (PMID 41295305, 2025). "The gain-of-function mutations of IDH1 and IDH2 genes commonly occur in GBM and acute myeloid leukemia (AML) and are associated with accelerated tumor cell proliferation and inhibited differentiation." (PMID 39199642, 2024). "This study investigated the signaling pathways involved in TF-1(R140Q) cell proliferation conversion as alternative therapeutic strategies to improve outcomes in patients with acute myeloid leukemia (AML) harboring IDH2/R140Q." (PMID 38347540, 2024). "Acute myeloid leukemia with NPM1, IDH2, and SETD2 mutations can mimic acute promyelocytic leukemia (APL) and poses a challenge for the early and accurate differentiation and diagnosis of APL with PML::RARA." (PMID 39432585, 2024). "For patients with a history of or a new diagnosis of acute myeloid leukemia (AML) at the time of ordering (n = 52), the most commonly mutated genes were RUNX1, SRSF2, and IDH2 (each with 16 variants)." (PMID 39691272, 2024). "To date, IDH1 and IDH2 inhibitors have been approved in acute myeloid leukemia and more recently in cholangiocarcinoma; nevertheless some clinical trials for other solid tumors with evidence of IDH1/2 mutations, including mCRC, are ongoing." (PMID 37064137, 2023). "The patient was diagnosed with acute myeloid leukemia (AML)-M5b accompanied by DNMT3A, FLT3-TKD, and IDH2 mutations, chest CT revealed pulmonary tuberculosis (TB)." (PMID 37384044, 2023). "Whether isocitrate dehydrogenase 2 (IDH2) R140 and R172 gene mutations affect the prognosis of patients with acute myeloid leukemia (AML) is controversial." (PMID 37291515, 2023). "In acute myeloid leukaemia, IDH1 and IDH2 mutations have been associated with the worse outcome, shorter overall survival, and normal karyotype." (PMID 35975235, 2022). "In low-grade glioma, secondary glioblastoma, and acute myelogenous leukemia, the oncogenic mutations in the two-isocitrate dehydrogenase (IDH) encoding genes (IDH1 and IDH2) have been identified." (PMID 36188571, 2022). "Mutations in IDH1 and IDH2 have frequently been found in acute myeloid leukemia patients, 7% for IDH1 and 14% for IDH2, separately." (PMID 35216362, 2022). "It is converted from α-KG by mutant isocitrate dehydrogenase (IDH1 and IDH2) that often occurs in glioma and acute myeloid leukemia (AML) patients." (PMID 36139121, 2022).
acute myeloid leukemia (continued). "Studies have confirmed that the active IDH2-mediated reductive TCA cycle in acute myeloid leukemia (AML) cells promotes the conversion of α-KG to isocitrate/citrate, thereby facilitating the synthesis of lipids from glutamine." (PMID 36497259, 2022). "Ivosidenib and enasidenib are targeted inhibitors of the IDH1 and IDH2 proteins, respectively, which have been confirmed to be efficient and tolerable in acute myeloid leukemia (AMLs) in previous studies." (PMID 35042566, 2022). "In acute myeloid leukemia (AML), IDH2 mutations are more prevalent than IDH1 mutations and usually affect codon R140." (PMID 34997121, 2022). "Currently, two FDA-approved IDH inhibitors, enasidenib (AG-221) and ivosidenib (AG-121), are used to treat acute myeloid leukemia harboring IDH1 and IDH2 mutations." (PMID 36160383, 2022). "Previous research has established the role of IDH1 and/or IDH2 in mediating reductive carboxylation in acute myeloid leukemia (AML) cells." (PMID 35740646, 2022). "Consistent with this notion, the mutant IDH1 (ivosidenib) and IDH2 (enasidenib) protein inhibitors have been initially approved by the U.S. food and drug administration (FDA) for relapsed/refractory acute myeloid leukemia (AML)-bearing IDH1 and IDH2 mutations." (PMID 35996504, 2021). "Recently, ivosidenib and enasidenib were approved by the FDA to treat acute myeloid leukemia with IDH1 and IDH2 mutations." (PMID 33816227, 2021). "Somatic point mutations in IDH1 and IDH2 genes have been found in glioma, glioblastoma multiforme (GBM) and acute myeloid leukemia (AML), prevalently concentrated in specific hot spots." (PMID 34065551, 2021). "Enasidenib (IDHIFA; AG-221), an IDH2 inhibitor, was approved by the US Food and Drug Administration (FDA) in 2017 for the treatment of adult patients with mutant IDH2 relapsed or refractory acute myeloid leukemia (R/R AML)." (PMID 34666780, 2021). "In acute myeloid leukemia (AML) TET2 mutations have been observed to be mutually exclusive with IDH1, IDH2, and WT1 mutations, all of them showing a similar impact on the transcription profile." (PMID 33805247, 2021). "Somatic heterozygous mutations in IDH1 and IDH2 occur in up to 60% of central conventional chondrosarcoma, 80% of WHO grade II–IV glioma, 20% of intrahepatic cholangiocarcinoma and 10% of acute myeloid leukemias (AML)." (PMID 34069550, 2021). "Selective IDH1 and IDH2 inhibitors have been approved for targeted therapy of acute myeloid leukemia." (PMID 32333643, 2020). "Genome-wide mutation analyses and high-throughput deep sequencing have identified that 70% of grade II-III gliomas and secondary glioblastomas, as well as 10% of acute myeloid leukemia (AML), have mutations in IDH1 or IDH2." (PMID 32764295, 2020). "Ivosidenib, a mutant IDH1 inhibitor, and enasidenib, a mutant IDH2 inhibitor, have been approved for treatment of relapsed/refractory acute myeloid leukemia (AML)." (PMID 33322351, 2020). "Isocitrate dehydrogenase isoform-1 (IDH1) and 2 (IDH2) mutations are considered to be associated with HIF-α stability in solid tumors, notably glioblastoma and acute myeloid leukemia (AML)." (PMID 33109235, 2020). "The mutant IDH2 inhibitor enasidenib has been approved by the U.S. Food Drug Administration (FDA) for the treatment of mutant IDH2 recurrent or refractory acute myeloid leukemia (AML)." (PMID 32509584, 2020). "IDH2/R140Q mutation is frequently detected in acute myeloid leukemia (AML)." (PMID 32245484, 2020). "Acute myeloid leukemia (AML) frequently harbors mutations in isocitrate 1 (IDH1) and 2 (IDH2) genes, leading to the formation of the oncometabolite (2R)-hydroxyglutaric acid (2R-HG) with epigenetic consequences for AML proliferation and differentiation." (PMID 33019704, 2020). "Acquired somatic mutations in the isocitrate dehydrogenase 1 and 2 genes (IDH1 and IDH2), have been reported in acute myeloid leukemia (AML), myelodysplastic syndromes (MDS), and chronic myeloproliferative neoplasms (MPN)." (PMID 32629801, 2020).
acute myeloid leukemia (continued). "Recently, a report showed that mutations of the isocitrate dehydrogenase (IDH) genes IDH1 and IDH2 can inactivate methylcytosine dioxygenase activity, resulting in DNA hypermethylation in acute myeloid leukemia cells." (PMID 31352437, 2019). "In the acute myeloid leukemia (LAML) cohort, 1.38% of missense mutations were in DNMT3A gene (p.R882H), 1.05% were IDH2 p.R140Q, and 0.79% were IDH1 p.R132C." (PMID 30890735, 2019). "IDH mutation occurs in 20% of acute myeloid leukemia (AML) patients, mainly including IDH1 R132, IDH2 R140, and IDH2 R172." (PMID 31660152, 2019). "Regarding the MPN/AML transformation, mutations in genes encoding epigenetics modifiers such as ASXL1, IDH1, IDH2, EZH2, and TET2 are associated with nearly 30% of secondary leukemia transformations and de novo acute myeloid leukemia." (PMID 29515972, 2018). "The first-in-class inhibitor of mutant IDH2 was approved by FDA for treatment of acute myeloid leukemia (AML) in 2017." (PMID 30283496, 2018). "For instance, glioblastoma or acute myeloid leukemia (AML) tumors that harbor IDH1/ IDH2 mutations are particularly dependent on the function of the GAC isoform for the anaplerotic replenishment of αKG, which is the source material used to generate the onco-metabolite 2-HG by these mutant enzymes." (PMID 28950000, 2017). "In acute myeloid leukemia (AML), mutations in DNA methylation regulators such as DNMT3A, TET2, IDH1 and IDH2 are frequent, and loss of function of TET2 and DNMT3A are early events in leukemogenesis." (PMID 26829670, 2016). "In the last 3 years, alone mutations in the genes TET2, IDH1, IDH2, DNMT3a, and EZH2 have all been found in patients with myeloproliferative neoplasms (MPNs), myelodysplastic syndromes (MDSs), and/or acute myeloid leukemia (AML)." (PMID 21811504, 2012). "APL-like acute myeloid leukemia with NPM1, IDH2, and SETD2 mutations was made." (PMID 39432585, 2024). "A 70-year-old man was diagnosed with acute myeloid leukemia with NPM1, IDH2, and SETD2 mutations." (PMID 39432585, 2024). "IDH2 mutations represent a possible therapeutic target: enasidenib, an anti-IDH2 agent, has recently been approved by FDA for patients with relapsed or refractory acute myeloid leukemia." (PMID 36431263, 2022). "Similar models recapitulate relevant mutations in Isocitrate dehydrogenase 1 and 2 (IDH1 and IDH2) mainly found in low-grade gliomas, secondary glioblastomas, and acute myeloid leukemia (AML), without the limitations of the earlier models." (PMID 36401282, 2022). "However, importantly, it has been reported that the decrease in 2-HG levels was not solely a predictive marker of the treatment response in an inhibitor of the mutant IDH2 drug trial of acute myeloid leukemia." (PMID 30791611, 2019). "The Agios Pharmaceuticals in association with Celgene has made much progress and their IDHIFA® (AG-221, Enasidenib, compound 1) is the first FDA approved mutant IDH2 selective inhibitor for adult patients with relapsed or refractory acute myeloid leukemia (AML)." (PMID 29439493, 2018). "AG-221 (enasidenib) is now approved for treatment of acute myeloid leukemia (AML) with IDH2 mutations, although enasidenib has not yet been tested in CCA." (PMID 30302397, 2018). "Moreover, in 20% of acute myeloid leukemia (AML), 50% of chondrosarcoma, 20% of intrahepatic cholangiocarcinoma, and 20% of angioimmunoblastic T-cell lymphoma, IDH1 or IDH2 are mutated as well." (PMID 27014623, 2016).
acute myeloid leukemia (continued). "IDH1 and IDH2 mutations have been found in other non-CNS neoplasms, including cholangiocarcinoma, acute myeloid leukemia, chondrosarcoma, and angioimmunoblastic T-cell lymphoma, but the pathogenesis in these entities remains unclear." (PMID 40546613, 2025). "Hotspot mutations in IDH1 and IDH2 occur in various human cancers, including GBM, acute myeloid leukemia (AML), and cholangiocarcinoma." (PMID 40563819, 2025). "For example, mutations in isocitrate dehydrogenase 1 and 2 (IDH1/2) occur in a subset of acute myeloid leukemia (AML) patients and IDH2 mutant leukemic cells produce elevated levels of the oncometabolite d-2-hydroxyglutarate (D2-HG)." (PMID 37361580, 2023). "Several types of cancer, including gliomas, acute myeloid leukemia, astrocytoma, and chondromas, have been found to harbor heterozygous missense mutations in the nicotinamide adenine dinucleotide phosphate (NADP+)-dependent IDH enzymes, mitochondrial IDH2 enzymes, and cytosolic IDH1 enzymes." (PMID 36286449, 2022). "As IDH mutations also frequently occur in acute myeloid leukemia (AML), although mostly affecting IDH2, some of these inhibitors have also been tested in AML samples and models." (PMID 36303101, 2022). "IDH mutations were also found in 10–20% of patients with acute myeloid leukemia (AML), with a low incidence in other cancers; the majority of these lesions involve arginine (R) residue mutations in IDH1 codon 132 (IDH1 R132) and residues 140 and 172 of IDH2 (IDH2 R140 and IDH2 R172)." (PMID 35765075, 2022). "Two recurrently mutated genes in CHIP and adult acute myeloid leukemia (AML) encode for isocitrate dehydrogenases 1 and 2 (IDH1 and IDH2)." (PMID 32948843, 2021). "Mutations of a single arginine in the catalytic site of IDH1 and IDH2 were observed in several malignancies, including glioblastoma, acute myeloid leukemia (AML) and cholangiocarcinoma, leading to a gain-of-function." (PMID 32610612, 2020). "Recently, the IDH1 inhibitor enasidenib, and IDH2 inhibitor ivosidenib, were approved in the treatment of patients with acute myeloid leukemia (AML)." (PMID 31803611, 2019). "Acute myeloid leukemia (AML) with a normal karyotype (CN-AML), which accounts for 40–50% of AML cases, commonly presents with genetic mutations in ASXL1, MLL, DNMT3A, TET2, IDH1 and IDH2 genes, all of which have important roles in epigenetic regulation." (PMID 24202321, 2013). "At the same time, other genetic alterations commonly found in acute myeloid leukemia, like DNMT3, TET2, NPM1, IDH1 or IDH2, are rarely detected, confirming the unique pathogenesis of APL." (PMID 38921185, 2024). "However, Bristol-Myers Squibb recently announced that the Phase III trial evaluating anticancer agent enasidenib (AG-221) for the treatment of IDH2 mutation-positive, relapsed, or refractory acute myeloid leukemia failed to meet the primary endpoint of overall survival." (PMID 36160383, 2022). "The treatment of acute myeloid leukemia (AML) has been rapidly evolved from conventional chemotherapy to target therapeutics such as FLT3-ITD and IDH2 inhibitors, thereby improving the complete remission rates over the past decade." (PMID 36355485, 2022). "While acute myeloid leukemia (AML) is still associated with a low cure rate, recent advances in understanding its molecular complexity have significantly improved therapy for subgroups of patients, including those harboring FLT3, IDH1, or IDH2 mutations." (PMID 35354920, 2022). "Mutations in the isocitrate dehydrogenase (IDH) family, notably IDH1 and IDH2, have been identified in several cancers such as grade II and III gliomas and acute myeloid leukemia (AML)." (PMID 34503108, 2021).
acute myeloid leukemia (continued). "Indeed, about 7.7% of acute myeloid leukemia (AML) possessed the IDH1 mutation, but prevalence rates vary between 15 and 33% if IDH2 are also considered." (PMID 26858939, 2016). "Further research is warranted to elucidate the genetic predispositions that may facilitate the transformation of leukemic MPNs into acute myeloid leukemia (AML), with emphasis on genes such as ASXL1, IDH1, IDH2, and SRSF2, among others." (PMID 39682300, 2024). "Interestingly, genetic alterations commonly found in acute myeloid leukemia like DNMT3, TET2, NPM1, IDH1 or IDH2 are rarely detected, suggesting that PML-RARA exhibits a distinct transformation pathway among AML." (PMID 32295268, 2020). "Mutations in tricarboxylic acid (TCA) cycle enzymes such as isocitrate dehydrogenase 2 (IDH2), succinate dehydrogenase, and fumarate hydratase are frequently found in human cancers, and the inhibitor of mutant IDH2, enasidenib, was approved by the FDA to treat acute myeloid leukemia." (PMID 31717493, 2019). "We used PCR-generated small CRISPR constructs to edit two genes (IDH2 and MYBL2) in hard-to-transfect hemopoietic cells, which are central to the progression of the devastating disease known as acute myeloid leukemia LMA (AML)." (PMID 37686539, 2023). "Mutations targeting genes encoding DNA methyltransferase (DNMT), TET family of DNA demethylases, and isocitrate dehydrogenase (IDH1, IDH2) that produce TET inhibitory metabolite, 2-hyoxyglutarate (2-HG), are found in more than half of acute myeloid leukemia (AML)." (PMID 34336831, 2021). "The IDH2 R172K mutation is found in up to 45% of AITL patients; it additionally is seen in acute myeloid leukemia (AML) and tends to confer worse prognoses to patients with de novo AML." (PMID 33801781, 2021). "Therefore, IDH1 and IDH2 inhibitors (ivosidenib and enasidenib) would regulate both DNA and histone demethylation, and have been approved by the FDA for the treatment of relapsed or refractory acute myeloid leukemia (AML)." (PMID 38044445, 2023).